TRAF1 (TNF receptor associated factor 1)
Diseases named in the same sentence as TRAF1 in open-access papers (continued):
Sharing a sentence is not in itself a finding about the gene and the disease.
TRAF1 also shares sentences with these, for which no sentence is quoted: prostate carcinoma (5 papers); Cerebral ischemia (3); autoimmune (2); hepatocellular carcinoma (2); lung adenocarcinoma (2); neuroblastoma (2); neurodegenerative disease (2); rheumatic diseases (2); schizophrenia (2); acute myeloid leukemia (1); African trypanosomiasis (1); AIDS (1); amyotrophic lateral sclerosis (1); astrocytic tumor (1); autoimmune liver disease (1); bladder cancer (1); brain tumour (1); carcinoid (1); cardiovascular disease (1); cholangiocarcinoma (1); colon adenocarcinoma (1); diabetes (1); enteritis (1); Epstein-Barr virus infection (1); gastritis (1); giant cell arteritis (1); head and neck squamous cell carcinoma (1); HTLV infection (1); infectious mononucleosis (1); Insulin resistance (1).
A further 24 diseases each share a sentence with TRAF1 in 1 paper.